PSEN1 (presenilin 1)
Diseases named in the same sentence as PSEN1 in open-access papers (continued):
Sharing a sentence is not in itself a finding about the gene and the disease.
familial Alzheimer disease (continued). "Mutations in presenilin 1 (PSEN1) are the leading cause of familial Alzheimer’s disease." (PMID 37239094, 2023). "Presently, PSEN1 gene is considered as the most common cause of familial Alzheimer’s disease (FAD)." (PMID 36158539, 2022). "Importantly, CYPs and FKBPs facilitate the proper folding and prevent aggregation of human pathogenic proteins such as the prion protein (PrP) and presenilin 1, which is linked with familial Alzheimer's disease." (PMID 34327811, 2021). "Presenilin 1 (PS1) mutations are the most common cause of familial Alzheimer’s disease (FAD)." (PMID 32296078, 2020). "Presenilin-1 knockout lines display distinct phenotypes from intron 4 deletion lines, including reduced mature nicastrin, arguing against a simple loss-of-function mechanism for familial Alzheimer’s disease mutations." (PMID 32395715, 2019). "We compared neurons derived from induced pluripotent stem cell (iPSC) lines of patients with early-onset familial Alzheimer’s disease (fAD), all caused by mutations in the PSEN1 gene; patients with late-onset sporadic Alzheimer’s disease (sAD); and three control individuals without dementia." (PMID 29191219, 2017). "Although dementias due to APP/PSEN1/PSEN2 mutations are classified as familial Alzheimer disease (FAD) and those due to mutations in BRI2/ITM2B as British and Danish dementias (FBD, FDD), data suggest that these diseases have a common pathogenesis involving toxic APP metabolites." (PMID 23217200, 2012). "Interestingly, in some mutations of presenilin 1 and 2 that are responsible for familial Alzheimer’s disease, disruption of intracellular Ca2+ homeostasis by the ER is the major measurable cellular consequence, as discussed later on." (PMID 23060904, 2012). "Mutations in presenilin-1 (Psen1) cause familial Alzheimer's disease (FAD)." (PMID 20863403, 2010). "Effects of familial Alzheimer’s disease (FAD)-mutant PSEN1 on endoproteolysis of C99 by γ-secretase." (PMID 39932776, 2025). "For instance, the expression of Presenilin 1 (PS1) progressively declines in the aged human brain, and PS1 mutations are the leading cause of early-onset familial Alzheimer’s disease." (PMID 40563323, 2025). "Inherited forms of AD (familial Alzheimer’s disease, FAD) are caused by autosomal dominant mutations in the amyloid precursor protein (APP) and presenilin (PSEN1 and PSEN2) genes." (PMID 38987603, 2024). "Among the cases in this group, familial Alzheimer’s disease (FAD) accounts for approximately 80% and is triggered by mutations in three primary genes: Presenilin-1 (PSEN1), Presenilin-2 (PSEN2), and the amyloid precursor protein (APP) gene." (PMID 38338859, 2024). "Mutations in the presenilin 1 gene, PSEN1, which cause familial Alzheimer’s disease alter the processing of amyloid precursor protein, leading to the generation of various amyloid-β peptide species." (PMID 36687397, 2023). "It is not unexpected that all induced pluripotent stem cell (iPSC) models of familial Alzheimer’s disease (FAD) have been created by introducing mutations in either the APP, PSEN1, or PSEN2 genes." (PMID 38031028, 2023). "Mutations in the Presenilin genes (PSEN1 and PSEN2) are the major cause of familial Alzheimer’s disease (AD), highlighting the importance of Presenilin (PS) in AD pathogenesis." (PMID 36710361, 2023). "Mutations in the Presenilin genes (PSEN1 and PSEN2) are associated with the major cause of familial Alzheimer’s disease." (PMID 35013145, 2022). "Mutations in presenilin 1 (PSEN1) or presenilin 2 (PSEN2), the catalytic subunit of γ-secretase, cause familial Alzheimer’s disease (fAD)." (PMID 33440141, 2021). "It was demonstrated that mice with presenilin-1 (PS1) mutations in microglia, specific to familial Alzheimer disease, show impaired hippocampal neurogenesis and emotional function." (PMID 34066618, 2021).
familial Alzheimer disease (continued). "One of the strongest motivations to study Notch signaling in these contexts is that rare mutations in genes that encode the catalytic subunits of the γ-secretase complex, Presenilin 1 (PSEN1) and PSEN2, cause rare early-onset familial Alzheimer’s disease." (PMID 32630239, 2020). "Mutations of three causative genes, namely presenilin 1 (PSEN1), presenilin 2 (PSEN2), and amyloid precursor protein (APP), have been identified as the major causes of early‐onset familial Alzheimer's disease (EOFAD)." (PMID 32767553, 2020). "Previous linkage analyses have revealed genes involved in the production of Aβ plaques, namely APP (Aβ precursor protein), PSEN1 (Presenilin-1) and PSEN2 (Presenilin-1), as the causal genes for early-onset familial Alzheimer's disease." (PMID 31032141, 2019). "Presenilin-1 (PS1; Psen1), the catalytic component of the γ-secretase complex, is mutated in most of familial Alzheimer’s disease (AD) cases." (PMID 31577226, 2019). "Mutations in presenilin-1 (PSEN1), encoding the catalytic subunit of the amyloid precursor protein-processing enzyme γ-secretase, cause familial Alzheimer’s disease." (PMID 32395715, 2019). "Presenilin 1 (PS1) expression in human brain gradually decreases with age and its mutations account for the most common cases of early-onset familial Alzheimer’s disease (FAD)." (PMID 30158533, 2018). "In this regard, the presenilin-1 (PSEN1)-associated γ-secretase interacts with STIM1 in human neuroblastoma SH-SY5Y cells, familial Alzheimer’s disease (FAD) patient skin fibroblasts, and mouse primary cortical neurons." (PMID 30088035, 2018). "In neuroblastoma SH-SY5Y cells and in familial Alzheimer’s disease patient skin fibroblasts, STIM1 is cleaved at the transmembrane domain by the presenilin-1-associated γ-secretase, leading to dysregulation of Ca2+ homeostasis." (PMID 30088035, 2018). "Mutations in the human genes PRESENILIN1 (PSEN1), PRESENILIN2 (PSEN2) and AMYLOID BETA A4 PRECURSOR PROTEIN (APP) have been identified in familial Alzheimer’s disease (AD)." (PMID 28636676, 2017). "5xFAD mice overexpress (under control of Thy1 promoter) both mutant human APP with the Swedish (K670N, M671L), Florida (I716V), and London (V717I) familial Alzheimer's disease (FAD) mutations and human PSEN1 harboring two FAD mutations (M146L and L286V)." (PMID 25883808, 2015). "Pathogenic mutations in the three known genes – the amyloid precursor protein (APP), presenilin 1 (PSEN1), presenilin 2 (PSEN2) – are known to cause familial Alzheimer's disease (AD) and tend to be associated with early-onset AD." (PMID 25333068, 2014). "The Alzheimer’s Precursor Protein (APP) is also cleaved by γ-secretase, and mutations in the two human presenilin genes encoding PS1 (PSEN1) and PS2 (PSEN2) are responsible for the majority of cases of early-onset familial Alzheimer’s disease (AD)." (PMID 23667524, 2013). "Since their discovery in 1995 and their association with early onset familial Alzheimer's disease (FAD), the presenilin genes PSEN1 and PSEN2 have been widely studied, and the complexity of their biological role is becoming increasingly evident." (PMID 22529981, 2012). "Mutations in the genes encoding presenilin 1 (PS1) and presenilin 2 (PS2) cause early-onset familial Alzheimer disease (AD)." (PMID 21206757, 2010). "In 1995, independent groups identified genetic linkage and mutations within PSEN1 (chromosome 14, 14q24.3) and PSEN2 (chromosome 1, 1q42.2) genes in several early onset familial Alzheimer’s disease (FAD) kindreds." (PMID 19415127, 2007). "Mutations in PSEN1 and PSEN2 genes account for the majority of cases of early-onset familial Alzheimer disease." (PMID 16930451, 2006). "The most extensively investigated include presenilin 1 (PSEN1), presenilin 2 (PSEN2), and amyloid precursor protein (APP) mutations, all of which contribute to elevated Aβ deposition and have been linked to familial Alzheimer’s disease." (PMID 41007636, 2025).
familial Alzheimer disease (continued). "Early-onset, familial Alzheimer’s disease (AD), with a prevalence of around 1%, is known to be associated with high-penetrance mutations in the genes coding for amyloid precursor protein (APP), presenilin 1 (PSEN1), and presenilin 2 (PSEN2)." (PMID 35736408, 2022). "Differentially regulated genes were then examined in Aβ-treated mouse hippocampal neurons as a validating primary in vitro neuronal model endogenously expressing nAChRs and in 5xFAD (familial Alzheimer’s disease) APP/presenilin 1 (PS1) mutant mouse hippocampus." (PMID 32231242, 2020). "Mutations in the PSEN1 and PSEN2 genes are the major cause of familial Alzheimer’s disease." (PMID 33302995, 2020). "Mutations in the presenilin (PSEN) encoding genes (PSEN1 and PSEN2) cause most cases of familial Alzheimer’s disease (AD); however, the underlying mechanism of pathogenesis remains unclear." (PMID 29989545, 2018). "Double transgenic mice APP/PS1 expressing a chimeric mouse/human APP (Mo/HuAPP695swe: APP Swedish mutation) and a mutant human presenilin 1 (PS1-dE9), both directed to central nervous system neurons, have been generated as animal models of familial Alzheimer's disease." (PMID 23205014, 2012). "In the present study, we investigated bone loss in mouse models of familial Alzheimer's disease harboring the Presenilin 1 (L166P) knock‐in mutation (PSEN1 KI), with or without the human amyloid precursor protein transgene (hAPP Tg+) known to induce brain amyloid pathology by 6 months." (PMID 41496612, 2026). "As a novel approach for treatment of early-onset familial Alzheimer’s disease, CRISPR-Cas9-mediated disruption of PSEN1 in human fibroblasts with the pathogenic PSEN1 M146L mutation can partially restore the disease-associated amyloid-β 42/40 increase, as well as reduce presenilin 1 levels." (PMID 35505961, 2022). "The striking discoveries, which moved the amyloid theory forward, are the linkage of the gene mutations in APP and presenilin, the catalytic core of γ-secretase complex (PSEN1 and PSEN2) to Familial Alzheimer’s disease (FAD)." (PMID 35865745, 2022). "Humanin was discovered in 2001 as a 24-mer peptide that inhibited neuronal cell death induced by neurotoxic amyloid-β (Aβ) peptides and by mutants of familial Alzheimer’s disease (FAD) genes, i.e., APP amyloid precursor protein (APP), presenilin-1 (PS1), and presenilin-2 (PS2)." (PMID 38132360, 2023).
dementia (95 papers, 2005 to 2025). Loss of intellectual abilities interfering with an individual's social and occupational functions. "In PSEN1 mutation carriers, a rapid and severe cognitive decline is prominent, as shown by the significant drop from mild to severe dementia within a two-year period." (PMID 40649976, 2025). "The PSEN1 Met139Valvariant has been reported across diverse ancestral backgrounds andis associated with either AD or atypical dementia, characterized by amnestic andbehavioral symptoms." (PMID 40386425, 2025). "The 3xTg-AD mouse model expresses three genes associated with dementia: PSEN1 m 146 V, APPSwe, and microtubule-associated protein tau (tauP 301 L)." (PMID 39273520, 2024). "It has been discerned that the PSEN1 variant (p.Thr291Pro), found in an individual presenting with spastic paraplegia, can later precede dementia onset in PSEN1-related familial AD25." (PMID 37577182, 2023). "Unexpectedly, however, lower educational attainment (less than three years) has also been associated with later onset of dementia in carriers of the PSEN1 E280A mutation." (PMID 37612284, 2023). "Report a 35-year-old male with childhood learning disability and early onset dementia who is homozygous for the A431E variant in the PSEN1 gene." (PMID 35959289, 2022). "Here, we study data on two types of dementia at Mild Cognitive Impairment (MCI) stage—familial AD patients (E280A mutation of the presenilin-1 gene) and elderly MCI patients at high risk of sporadic AD, both with age-matched controls." (PMID 37555153, 2022). "At best, the 3xTg-AD model is representative of early-onset familial AD caused by genetic mutations in APP and PSEN1, which account for an estimated 1% or less of all AD-related dementia cases." (PMID 33472690, 2021). "The clinical features of the family members were far less aggressive than the dementia phenotypes caused by PSEN1 mutations, and more closely resembled LOAD." (PMID 33129344, 2020). "A Swedish family with six cases of documented dementia across four consecutive generations was first described in 1946 and genetic analysis was performed in 1998 which disclosed PSEN1 c.438G > C, p.Met146Ile mutation." (PMID 33188256, 2020). "While PSEN1-E280A carriers develop dementia at the median age of 49 years, carrying a mutation on the AD risk modifier ApoE3 (R136S) delayed dementia significantly, until the 7th decade, demonstrating that Aβ accumulation is not enough to develop AD." (PMID 33343276, 2020). "We next compared these variants with 106 susceptible genes for AD, AD-related pathological traits and other dementia and found only one missense mutation in PSEN1 (c.356C > T, p.T119I) was carried by the affected individuals." (PMID 32477171, 2020). "Whole genome sequencing analysis evaluated rare coding mutations in susceptible genes for various types of dementia and supported the role of PSEN1 as a causal gene." (PMID 32477171, 2020). "In this study, we comprehensively analyzed susceptible genes for various types of dementia through whole genome sequencing and confirmed the mutation in PSEN1 (c.356C > T, p.T119I) as the primary causal variant for a non-amnestic AD." (PMID 32477171, 2020). "Whole genome sequencing excludes the presence of rare mutations in other known susceptible genes for dementia and supports the role of PSEN1 as a causal gene in this pedigree." (PMID 32477171, 2020). "Additional mutations in the PSEN1 gene including p.G217D, p.V272A, and p.L420R have been associated with dementia and parkinsonism." (PMID 29692703, 2018). "The functional experiment demonstrated that PSEN1 c.857-1G>A caused genomic deletion of presenilin 1 exon 9, which led to the serious form of dementia." (PMID 30090657, 2018). "The p.Gly206Ala variant (NM_000021.3:c.617G>C) in PSEN1 was the most frequent and had the strongest effect on the risk of dementia." (PMID 25333068, 2014).
dementia (continued). "Mutations in any of 4 genes are causative of early onset dementias due to either AD (presenilin 1 [PSEN1], presenilin 2 [PSEN2], and amyloid precursor protein [APP]) or prion disease (prion protein gene, PRNP)." (PMID 21193246, 2012). "In 2017, Carecchio and colleagues reported on a case of a de novo yet unknown PSEN1 mutation (p.Ser170Phe) presenting with a predominant motor phenotype, an early-onset dystonia-parkinsonism, later complicated by dementia and myoclonus, with brain MRI mimicking basal ganglia iron accumulation." (PMID 37648940, 2023). "In addition to human studies supporting improvements in cognition, ashwagandha ameliorated cognitive deficits in aged transgenic mice with amyloid precursor protein (APP)/presenilin 1 (PSEN1) variants known to be associated with dementia and other animal models." (PMID 35517054, 2022). "Finally, perturbed calcium homeostasis might play an important role in mitochondrial dysfunction and oxidative stress in dementia patients, especially for patients correlated with presenilin-1 mutations." (PMID 29094046, 2017). "When these data is combined with data we have previously published we conclude that among 105 dementia patients, 5.7% are attributable to PSEN1 mutations (6/105), 2.9% (3/105) to C9ORF72 and TREM2 each, and 0.95% (1/105) to MAPT, GRN and NOTCH3 each, while 85.7% (90/105) remain unclear." (PMID 27632209, 2016). "This highlights the early involvement of the frontal lobes in PSEN1-related dementia, despite its strong Alzheimer’s phenotype." (PMID 40649976, 2025). "Her early work focused on Mendelian forms of dementia and led to the identification of mutations in APP, PSEN1, and MAPT as causes of AD and FTD." (PMID 38170841, 2024). "Basically, it is known that autosomal cases (i.e., presenilin-1 and 2, APP) linked to AD, the most common cause of dementia, represent a very small percentage of AD cases (≤1%) versus those with a sporadic late-onset disease." (PMID 39064140, 2024). "Other NVU cell-type DEGs formed connections with both dementia and AD, including Plcg2 (microglia), Dhcr24 (astrocytes), and Psen1 (neurons)." (PMID 39456952, 2024). "As a PSEN1 E280A carrier, the age of dementia onset was expected to take place at least 25 years earlier and shown more extended generalized cortical pTau pathology." (PMID 37264439, 2023). "In a previous study of 109 PSEN1 E280A mutation carriers, those who had an APOE e4 allele had an earlier age of dementia onset than those who did not5." (PMID 37612284, 2023). "PSEN1/2 mutant carriers have early-onset dementia, but autosomal dominant and late-onset AD have different behavioral and pathophysiology." (PMID 37045867, 2023). "In this context, it is worth mentioning that several genes linked to dementia, including APP, PSEN1, PSEN2, and ITM2b, play a physiological role in glutamatergic transmission and that mutations linked to familial dementia alter this physiological functions." (PMID 33434745, 2021). "PPI network that demonstrated proteins such as PSEN1, PSEN2, APP, MAPT, and C9orf72 had abundant interactions with other proteins, which was consistent with the important roles of these dementia pathogenic genes." (PMID 34720994, 2021). "Here, we evaluate BMAA exposure by investigating transcription signatures using PCR for dolphin genes homologous to those implicated in AD and related dementias: APP, PSEN1, PSEN2, MAPT, GRN, TARDBP, and C9orf72." (PMID 34678990, 2021). "Familial Alzheimer’s Disease (FAD) caused by Presenilin-1 (PS1) mutations is characterized by early onset, cognitive impairment, and dementia." (PMID 32848702, 2020). "Several of the connections we found in our network analysis, such as GSK3B, MAPT, ADAM17, and PSEN1 are also involved in other dementias than AD." (PMID 31797941, 2019). "Using clinical and genetic approaches, our findings indicate that mutations in PSEN1 and APP can lead to atypical clinical symptoms at an early stage and a serious form of dementia." (PMID 30090657, 2018).